INS (insulin)
Diseases named in the same sentence as INS in open-access papers (continued):
Sharing a sentence is not in itself a finding about the gene and the disease.
Insulin resistance (continued). "Insulin resistance is a pathological condition characterized by the reduced responsiveness of target tissues—such as muscle, liver, and adipose tissue—to insulin." (PMID 39942757, 2025). "All treatments were accompanied by insulin to simulate the hyperinsulinemia state in insulin resistance." (PMID 40862774, 2025). "Type 2 Diabetes Mellitus (T2D) is a chronic metabolic disorder and a significant global health concern, marked by insulin resistance and impaired insulin secretion that result in elevated blood glucose levels." (PMID 40854653, 2025). "Dysfunction of gut microbiota impairs fat metabolism, enhances fat accumulation, promotes inflammation, elevates blood glucose and insulin levels, increases free radical production, and contributes to insulin resistance." (PMID 41157258, 2025). "For the normal development of the placenta, more insulin should be needed to compensate for obesity-induced insulin resistance." (PMID 40725223, 2025). "Visceral adiposity contributes to insulin resistance through changes in adipokine secretion, an increase in pro-inflammatory cytokines, and impairment of insulin signaling." (PMID 40565464, 2025). "This can lead to the burst of reactive oxygen species, lipid metabolism disorders, insulin resistance, and insufficient insulin secretion by pancreatic β-cells." (PMID 40061953, 2025). "Conversely, in DN rats experiencing insulin resistance, normal insulin function is hindered despite elevated insulin secretion." (PMID 40182806, 2025). "Abnormal glucose metabolism, characterized by disrupted blood glucose and elevated insulin resistance, weakens insulin's anti‐inflammatory effect, promoting pro‐inflammatory factor release." (PMID 40739795, 2025). "During insulin resistance, insulin’s inhibitory effect on lipolysis is suppressed, leading to increased release of free fatty acids (FFAs)." (PMID 41272918, 2025). "A cross-sectional study to investigate the effects of SGLT-2 inhibitors on insulin secretion and resistance showed improvement in β-cell function and a 21% (p = 0.008) reduction in insulin resistance." (PMID 40559405, 2025). "We have previously shown that only 2 weeks of high‐intensity interval training decreases insulin‐stimulated BGU in middle‐aged people with insulin resistance." (PMID 40926735, 2025). "In turn, insulin-mediated effects on adipose tissue promote visceral adiposity, insulin resistance, dyslipidemia, and hypertension." (PMID 40303518, 2025). "HOMA IR is widely accepted in both clinical and research settings for estimating insulin resistance from fasting glucose and insulin levels, providing valuable insights into the metabolic and cognitive consequences often observed in OSA." (PMID 40565316, 2025). "T2DM is a chronic metabolic disorder in which the pancreas secretes an insufficient amount of insulin in response to systemic insulin resistance." (PMID 40408591, 2025). "As is well known, T2DM rats have insufficient insulin secretion and insulin resistance, and there are increased expressions of GLUT2 and SGLT-1 in the intestine of T2DM rats." (PMID 40006017, 2025). "Obesity contributes to insulin resistance, which necessitates higher insulin doses to maintain glucose levels." (PMID 40553147, 2025). "The accumulation of iron by adipocytes is an important factor of insulin resistance, considering that iron is a key modulator of the synthesis of insulin-regulating adipokines." (PMID 39941760, 2025). "Improving insulin sensitivity, and thus insulin resistance and overall health, can be achieved by increasing dietary protein content and reducing the GI value." (PMID 40775771, 2025). "The SIDD group, like the previous subtypes, shows deficient insulin secretion (low HOMA2-B), although with the onset of insulin resistance." (PMID 41255523, 2025).
Insulin resistance (continued). "This reflects the core feature of insulin resistance: despite normal insulin levels, target tissues fail to adequately promote glucose uptake, utilization, and storage via GLUT4, impairing the normal hypoglycemic response and raising blood glucose." (PMID 41357227, 2025). "The two biflavones, amentoflavone and bilobetin, which differ only in the C8 position, with the former being hydroxyl and the latter methoxy, were both able to improve insulin resistance and aberrant insulin secretion." (PMID 40298635, 2025). "These MΦs secrete pro-inflammatory cytokines such as TNF-α, IL-6, and IL-1β, which inhibit insulin signaling in adipocytes and promote insulin resistance." (PMID 41602577, 2025). "The relationship between changes in the apolipoprotein level and body composition, fasting blood glucose, insulin, and insulin resistance was also assessed." (PMID 40123054, 2025). "Offspring insulin resistance and β-cell function were assessed at nine years of age using serum insulin, C-peptide, and glucose concentrations measured during an oral glucose tolerance test." (PMID 40544417, 2025). "A prodigious number of primary research articles have utilized this technique for inducing insulin resistance, and many of these manuscripts have focused on methods of restoring the palmitate-mediated reduction in insulin signaling." (PMID 41305671, 2025). "At the age of 12 weeks, the ob/ob mice displayed an increased body weight associated with hyperglycemia, as well as a cardiac insulin resistance reflected by decreased insulin-stimulated Ser473-AKT phosphorylation compared to WT mice." (PMID 40492240, 2025). "Hyperinsulinemia in PCOS is often attributed to insulin resistance, based on the concept that impaired insulin-mediated glucose disposal would induce compensatory insulin hypersecretion." (PMID 40013621, 2025). "Obese individuals develop insulin resistance, which is characterized by impaired insulin sensitivity by tissues, leading to hyperglycemia and hyperinsulinemia, which can lead to serious complications such as neuropathies, cancer, and cardiovascular disorders." (PMID 40564946, 2025). "Many of these biomarkers originate from amino acids and have been shown to disrupt both energy metabolism and insulin signaling, contributing to hyperglycemia and insulin resistance." (PMID 41590635, 2025). "Among glucose–insulin parameters, obese patients with SZ had significantly higher fasting insulin and the Homeostatic Model Assessment of Insulin Resistance (HOMA-IR) index levels, whereas glucose was lower." (PMID 40141202, 2025). "Type 2 diabetes mellitus (T2DM) represents a multifaceted metabolic disorder defined by persistent hyperglycemia arising from a combination of peripheral insulin resistance and inadequate compensatory insulin secretion." (PMID 41268160, 2025). "The pro-inflammatory cytokines are excessively secreted from WAT in either genetic-based or diet-induced obese mice, which in turn interrupt insulin action in adipocytes, contributing to the onset and development of insulin resistance." (PMID 40368890, 2025). "Metabolic Status: Furthermore, metabolic health status (e.g., insulin resistance and type 2 diabetes) independently modulates these responses, with insulin-resistant individuals often displaying reduced MFO even when matched for BMI." (PMID 41590220, 2025). "Insulin resistance, as observed in type 2 diabetes, impairs mitochondrial function, underscoring insulin’s essential role in maintaining mitochondrial health." (PMID 40733109, 2025). "Further research was conducted on the Clu content in high density lipoprotein (HDL) of subjects with lean insulin sensitivity, lean insulin resistance, and obese insulin resistance." (PMID 40438587, 2025).
Insulin resistance (continued). "The connection between insulin resistance and AD has solidified the concept of “Type 3 Diabetes,” which posits that insulin resistance in the brain, combined with an impaired capacity to eliminate Aβ, plays a critical role in the onset of AD." (PMID 40724942, 2025). "Insulin resistance selectively inhibits the hypoglycemic effects of insulin while continuing de novo lipogenesis through the activation of SREBP-1." (PMID 40723862, 2025). "Insulin resistance (IR) is defined as an alteration in the biological response of target cells to insulin, which translates into a reduction in glucose uptake by muscle and adipose tissues." (PMID 41255523, 2025). "These miRNAs exhibited negative correlations with placental weight and positive correlations with UCP insulin and insulin resistance (HOMA‐IR)." (PMID 40013652, 2025). "Risk of postmenopausal breast and other cancers have been shown to be specifically linked to excess body fat, particularly when in combination with increased serum insulin and insulin resistance." (PMID 41146360, 2025). "Enpp1, which is known to inhibit insulin signaling and potentially leads to insulin resistance, was shown as a prime target of G4 repression." (PMID 40913227, 2025). "Insulin resistance happens mainly at the level of insulin-sensitive tissues, such as the liver, muscle, and fat, and can be caused by multiple mechanisms." (PMID 40362446, 2025). "Several proposed mechanisms by which Se ameliorates insulin resistance include the activation of kinases involved in the insulin signaling cascade and the enhancement of peroxisome proliferator-activated receptor gamma (PPAR-γ) mRNA expression." (PMID 40564877, 2025). "In relation to insulin resistance, several molecular mechanisms contribute to the impaired insulin signaling observed in both PCOS and cardiometabolic disorders." (PMID 40149685, 2025). "In agreement with our previous published reports, DE-71-exposed female offspring displayed glucose intolerance and significantly greater insulin-to-glucose ratios, which is used as an index of insulin resistance, when compared to the control group." (PMID 39520540, 2025). "This seems to be due to increased peripheral sensitivity to insulin, as evidenced by the statistically significant improvement in all the indices of insulin resistance considered." (PMID 39347907, 2025). "The AMPK-dependent pathway is particularly relevant in conditions like insulin resistance, where insulin signaling is impaired, as it provides an alternative route for glucose transport." (PMID 40932616, 2025). "In contrast, a 2015 meta-analysis identified a significant association between this variant and elevated circulating insulin levels and HOMA-IR in Caucasian populations with obesity, suggesting a potential genetic predisposition to insulin resistance." (PMID 40732969, 2025). "The fasting glucose (FG), insulin levels, homeostatic insulin resistance and glycated haemoglobin were measured in all experimental groups during the 12-week treatment period." (PMID 39861423, 2025). "Firstly, excess body fat, particularly visceral fat, leads to insulin resistance, where the body’s cells become less responsive to insulin, resulting in elevated blood glucose levels." (PMID 40217852, 2025). "Its potent antioxidant activity further enhances insulin sensitivity by reducing oxidative stress, a key contributor to insulin resistance." (PMID 39942757, 2025). "Anticalcineurin agents (especially tacrolimus, to a lesser extent cyclosporine) induce apoptosis of pancreatic beta cells, reducing insulin secretion and inducing insulin resistance." (PMID 40142909, 2025). "Further studies are needed to investigate the effect of honey on insulin signaling pathways and insulin resistance or glucose homeostasis following CUMS." (PMID 40656624, 2025).
Insulin resistance (continued). "Fasting glucose, fasting insulin, and homoeostasis model assessment of insulin resistance (HOMA-IR), an index of insulin resistance, were significantly increased in HFD-fed mice compared with normal chow diet (NC)-fed mice (p < 0.01)." (PMID 39803918, 2025). "Local insulin resistance in muscle can precipitate systemic insulin resistance because skeletal muscle is responsible for approximately 70%–80% of insulin‐dependent glucose uptake." (PMID 40641114, 2025). "Insulin resistance is usually attributed to an increased consumption of carbohydrates, which in turn promotes hyperglycemic states, elevating insulin levels and viciously leading the individual to develop this resistance." (PMID 39859069, 2025). "These factors of inflammation activate the intracellular serine/threonine kinases inhibitors and thereby inhibit important proteins of the insulin-signaling pathway leading to insulin resistance." (PMID 39859066, 2025). "Non-insulin-based indices provide a more practical approach for assessing insulin resistance in large populations." (PMID 40416870, 2025). "With early glycemic control, there is a reduction in fasting glucose and insulin levels and, consequently, a decrease in insulin resistance." (PMID 40902424, 2025). "Obesity-induced insulin resistance further compromises cognitive function by reducing insulin transport into the brain, impairing glucose metabolism, and promoting amyloid accumulation." (PMID 40337166, 2025). "Taken together, baicalin alleviates insulin resistance and regulates hepatic glucose metabolism by activating the insulin signaling pathway." (PMID 40538532, 2025). "A fundamental characteristic of PCOS is insulin resistance, in which elevated insulin levels stimulate the ovaries to produce excessive androgenes, resulting in irregular menstruation and impaired ovulation." (PMID 40718420, 2025). "OS also enhances insulin resistance through mitochondrial dysfunction, as normal mitochondrial function is crucial for insulin signaling." (PMID 40599237, 2025). "Insulin resistance (IR) refers to the weakened/diminished biologic response of target tissues (primarily the liver, skeletal muscle, and adipose tissue) to insulin stimulation." (PMID 41473239, 2025). "These inflammatory mediators impair insulin signaling pathways, thereby reducing glucose uptake and contributing to systemic insulin resistance." (PMID 41268160, 2025). "According to KEGG pathway enrichment, pyruvate metabolism, lipid and atherosclerosis, insulin signaling pathway, fatty acid biosynthesis, bile secretion, glucagon signaling pathway, and insulin resistance were involved." (PMID 40989883, 2025). "High blood glucose levels often coexist with insulin resistance—a condition in which cells (especially muscle and adipocytes) respond poorly to insulin." (PMID 41149623, 2025). "Their findings regarding fasting insulin and HOMA-IR values closely align with ours, suggesting that insulin resistance plays a consistent pathogenic role across different Asian populations." (PMID 41523516, 2025). "These cytokines create a detrimental inflammatory environment within the pancreas, leading to β-cell apoptosis and reduced insulin secretion, which further exacerbates insulin resistance." (PMID 40958722, 2025). "Second, although insulin's direct stimulation of hepatic lipid synthesis was reduced in insulin resistance, the elevated hepatic glucose output provides substrates that drive hepatic lipid synthesis, ultimately leading to increased hepatic lipid accumulation." (PMID 40181314, 2025). "Increased FA deposition in muscle promotes insulin resistance, inhibiting insulin-mediated glucose uptake into muscle and further exacerbating the glucose delivered to the liver and fueling more DNL." (PMID 39928502, 2025). "Specifically, TNF-α exacerbates insulin resistance by activating the NF-κB signaling pathway and inhibiting the action of insulin." (PMID 40351422, 2025).
Insulin resistance (continued). "A recent meta-analysis of 17 randomized controlled trials involving 1,049 participants demonstrated that probiotic supplementation significantly lowered fasting blood glucose, insulin levels, and insulin resistance in women with polycystic ovarian syndrome." (PMID 40255841, 2025). "These metabolic disturbances include, but are not limited to, insulin resistance, impaired insulin secretion and progressive development of hyperglycemia, common features of T2D." (PMID 40001928, 2025). "Longitudinal prospective cohorts that track insulin levels, insulin resistance, and bone health over time are essential to clarify the causal and temporal relationships." (PMID 40564223, 2025). "The plasma leptin levels in FRUCT animals seem to be directly correlated with elevated plasma insulin concentration and insulin resistance observed in this group of animals." (PMID 40227203, 2025). "When insulin action is impaired, the liver cannot effectively lower blood sugar, leading to insulin resistance." (PMID 40969371, 2025). "Type 2 diabetes mellitus (T2DM) is a metabolic disease characterized by persistent hyperglycemia, typically resulting from insufficient insulin secretion or insulin resistance (IR)." (PMID 40271065, 2025). "Genetic testing allows medical professionals to sort patients so they can start insulin treatment immediately for people with beta-cell deterioration and enhance insulin-sensitizing medications for those with insulin resistance." (PMID 40225541, 2025). "Collagen has been shown to actively drive insulin resistance, possibly through regulation of the insulin signaling pathway." (PMID 40309438, 2025). "Insulin resistance (IR), a pathological state where tissue has decreased sensitivity to insulin, is the initiating link in type 2 diabetes." (PMID 41153635, 2025). "This shift toward a pro-inflammatory state disrupts insulin signaling pathways, promoting systemic insulin resistance, a key driver of T2D." (PMID 41226298, 2025). "In particular, both heterogenous Nedd4 KO (Nedd4+/−) and Itch KO (Itch−/−) mice display improved obese-related insulin resistance, as evaluated by the insulin tolerance test (ITT)." (PMID 41009733, 2025). "Insulin resistance is a key mechanistic link—skeletal muscle is the major insulin-sensitive tissue, and with sarcopenia, there is less muscle to uptake glucose, exacerbating insulin resistance." (PMID 40870469, 2025). "Inflammatory factors from adipose tissue (TNF-α, IL-6) disrupt insulin signaling, exacerbating lipid synthesis and insulin resistance." (PMID 40129589, 2025). "Studies have shown that mitochondrial dysfunction induces insulin resistance in adipocytes via impaired insulin signaling pathways, which subsequently leads to reduced glucose uptake and the development of insulin resistance." (PMID 39269560, 2025). "Insulin resistance is the state where insulin stimulation is impaired in the insulin‐targeting tissues, and it plays an important role in T2D development." (PMID 41065424, 2025). "The leptin-to-adiponectin ratio, or LAR, is a composite biomarker that represents the balance between leptin (pro-inflammatory, insulin-resistance-promoting) and adiponectin (anti-inflammatory, insulin-sensitizing)." (PMID 40722840, 2025). "As seen in the sex-stratified model, the BMI-stratified analysis showed a significant positive association between HOMA-IR and HOMA-B, reflecting a compensatory increase in insulin secretion in response to insulin resistance." (PMID 40843316, 2025). "Key characteristics of T2D encompass diminished tissue sensitivity to insulin, a condition referred to as insulin resistance (IR), and failure of pancreatic β-cells to secrete sufficient insulin." (PMID 40004147, 2025). "It had effectively reversed insulin resistance induced by STZ treatment via augmenting insulin signaling." (PMID 41226821, 2025).